STAT3 (signal transducer and activator of transcription 3)
Diseases named in the same sentence as STAT3 in open-access papers (continued):
Sharing a sentence is not in itself a finding about the gene and the disease.
triple-negative breast carcinoma (continued). "HMGN4 plays a critical function in STAT3-mediated carcinogenesis in triple-negative breast cancer (TNBC) and it may well be a potential new focus for anti-TNBC therapy." (PMID 36568211, 2022). "The authors demonstrate that STAT3/IL6 stimulation governed the DRD2-induced stem cell self-renewal in triple-negative breast cancers, while the induction of cell-cycle arrest at G1 and reduction in cell proliferation and viability were reported to be independent of DRD2." (PMID 34422720, 2021). "Further survival analyses of triple-negative breast cancer datasets showed that high TrkA activation and high co-activation, but not STAT3 activation, were associated with shortened time to develop brain metastasis." (PMID 34066153, 2021). "Furthermore, the increase in ALDH expression has been demonstrated to be a consequence of STAT3 activity, specifically in triple-negative breast cancer as outlined by Arnold and collaborators." (PMID 34141616, 2021). "Hence, the combination of therapy against mTOR and STAT3 is a promising prospect for the treatment of triple negative breast cancer." (PMID 32669950, 2020). "Potential STAT3 inhibitors can decrease the production of ROS and down-regulate phosphorylation of STAT3 and Bcl-2, restoring sensitivity to radiation, which offers an effective approach for treating triple-negative breast cancer cells." (PMID 32872659, 2020). "First, therapeutic strategies involving STAT3 inhibition could enhance the efficacy of anti-PD-L1/PD-1 monoclonal antibodies, which recently proved efficacy in patients with metastatic triple negative breast cancer." (PMID 31581535, 2019). "Finally, STAT3 regulation by autophagy was previously found to confer sensitivity to autophagy blockade in triple-negative breast cancer cells." (PMID 31383875, 2019). "Notably STAT3 is often constitutively activated in triple negative breast cancers and these cancers display a profile of cell surface markers that is similar to that of breast CSCs." (PMID 29588647, 2018). "Using publicly available array profiling data, we could show here that in triple negative breast cancer, which is a representative cancer with constitutive STAT3 activation, higher mRNA levels show a trend for worse relapse-free survival (RFS)." (PMID 29588647, 2018). "Given recent evidence showing that metformin targets STAT3 pathways in triple negative breast cancer cells, and that metformin is widely available and in common clinical use (for type 2 diabetes), metformin has the potential for rapid therapeutic implementation for STAT3-overexpressing cancers." (PMID 28114390, 2017). "Indeed, recently a small molecule inhibitor targeting Bcl6 has been developed, and combining this with a Stat3 inhibitor resulted in enhanced cell killing in triple negative breast cancer cell lines." (PMID 26187947, 2015). "miR-483-5p has also been found to have a carcinogenic role in triple-negative breast cancer in that it inhibits SCOS3 (suppressor of cytokine signaling 3) gene expression that may trigger the pathway of STAT3, NF-κB, and primary inflammatory cytokines such as TNF-α, IL-6, MCP-1, and IL-1β." (PMID 37298699, 2023). "Besides, a most recent study revealed MNX1-AS1 could enhance the aggressiveness of triple-negative breast cancer cells through interacting with Stat3 and increasing its phosphorylation in a p-JAK-dependent manner." (PMID 33685348, 2021). "In addition, previous results have revealed metformin could block STAT3 phosphorylation in triple-negative breast cancers." (PMID 24789104, 2014). "Moreover, metformin could inhibit cell growth and induce apoptosis in triple-negative breast cancers by blocking STAT3 phosphorylation." (PMID 24789104, 2014). "In summary, we have demonstrated some of the effects of CDK8 inhibition on CDK8, E2F1, STAT3, and Mcl-1 proteins in MDA-MB-468 triple-negative breast cancer cells." (PMID 41596544, 2026).
triple-negative breast carcinoma (continued). "Using androgen-independent prostate cancer (DU145) and triple-negative breast cancer (KPL-4) cell lines, we demonstrated constitutive activation and reciprocal regulation of STAT3, PKM2, and HIF-1α." (PMID 41828578, 2026). "In this study, expression of the E7 oncogene in triple-negative breast cancer cells led to a decrease in the expression of the STAT4, JAK2, and STAT3 genes, which are key mediators of the immune response." (PMID 40733498, 2025). "In triple-negative breast cancer, picrasidine G has been found to reduce cancer cell proliferation by inhibiting the EGFR/STAT3 signaling pathway." (PMID 37686036, 2023). "Treatment of triple negative breast cancer (TNBC) cells with the compounds inhibited both constitutive and ligand-induced Stat3 activation, and perinuclear aggregation, which led to tumor cell death." (PMID 35276290, 2022). "In a systematic review, the Signal transducer and activator of transcription 3 (STAT3) was activated through the LKB1 and AMPK pathway which induced apoptosis in triple-negative breast cancer cells." (PMID 35455439, 2022). "The results suggested that SARS-CoV-2 M protein induced the mobility, proliferation, stemness and in vivo metastasis of a triple-negative breast cancer (TNBC) cell line, MDA-MB-231, which are involved in the upregulation of NFκB and STAT3 pathways." (PMID 35747796, 2022). "We previously identified STAT3 as a novel transcriptional regulator of X-ray cross-complementing group 1 (XRCC1), an essential scaffold protein in base excision repair in triple-negative breast cancers." (PMID 35457130, 2022). "The elevated HLA-F-AS1 expression induced by STAT3 promoted cell growth and stemness characteristics via sponging with miR-541-3p to upregulate the expression of a TraB domain (TRABD) containing triple-negative breast cancer cells." (PMID 34068010, 2021). "Treatment with recombinant human G-CSF protein or stable expression of human G-CSF in triple-negative breast cancer (TNBC) cell lines enhanced epithelial–mesenchymal transition, migration, and invasion of cancer cells, by activating Stat3." (PMID 32242230, 2020). "Here, the authors illustrate that in triple negative breast cancer models Wwox suppresses metastasis and proliferation via the JAK2/STAT3 pathway." (PMID 30154439, 2018). "In triple-negative breast cancer cell lines, metformin was shown to oppose both JAK/STAT3-Tyr activity and STAT3-Ser phosphorylation." (PMID 30054579, 2018). "Inhibition of acetyl-STAT3 by SH-I-14 resulted in disruption of STAT3-DNMT1 interaction, de-methylation of TS genes’ promoter regions in triple-negative breast cancer (TNBC) cells in vitro, re-expression of TS genes and inhibition of TNBC tumor growth in vivo." (PMID 29137356, 2017). "SH-I-14 and resveratrol inhibit the acetylation of STAT3 (K685) and disrupt the interaction between STAT3 and DNMT1, which leads to de-methylation of tumor suppressor genes promoter regions in triple-negative breast cancer (TNBC)." (PMID 28978186, 2017). "In triple-negative breast cancer (TNBC), ZFAS1 downregulation correlates with suppressed proliferation/EMT through STAT3 phosphorylation inhibition, whereas it’s silencing paradoxically activates STAT3-driven tumorigenesis." (PMID 41450817, 2026). "In the context of triple-negative breast cancer, WWOX inhibits STAT3-dependent tumor cell growth and metastasis by modulating the IL-6/JAK2/STAT3 signaling pathway, leading to the downregulation of p-STAT3 target genes." (PMID 41228229, 2025). "Moreover, NONO contributes to oncogenesis, chemotherapy resistance, and poor prognosis in triple-negative breast cancer (TNBC) by modulating Epidermal Growth Factor Receptor (EGFR) and Signal Transducer And Activator Of Transcription 3 (STAT3) stability." (PMID 40943463, 2025).
triple-negative breast carcinoma (continued). "Moreover, niclosamide also acted as a potent radiosensitizer through inhibiting signal transducer and activator of transcription 3 (STAT3) and B-cell lymphoma-2 (Bcl-2) and increasing ROS generation in triple-negative breast cancer cells." (PMID 34539975, 2021). "STAT3, a transcription factor in JAK-STAT signaling, was another target of VGLL4, and binding of VGLL4 to STAT3 repressed its transcriptional activity and cell growth in triple-negative breast cancer." (PMID 32793503, 2020). "Importantly, our data also show the cooperative regulation of RhoU, and of RhoU-mediated triple negative breast cancer cells migration and invasion, by WNT/JNK1/SP1 and STAT3." (PMID 30654518, 2019). "In addition, at least in triple-negative breast cancer cells in vitro, metformin can reduce the activation (phosphorylation) of STAT3 but does not alter STAT3 expression levels." (PMID 38543182, 2024). "Additionally, NONO, another RNA binding protein, is found to bind to STAT3 mRNA, increasing its levels in triple-negative breast cancer." (PMID 38164170, 2024). "Additionally, in triple-negative breast cancer, a micropeptide named ASRPS has been identified and shown to regulate the STAT3/VEGF signalling pathway, bind directly to STAT3, inhibits STAT3 phosphorylation, and reduce VEGF expression, thereby inhibiting tumour angiogenesis." (PMID 38622617, 2024). "Moreover, in A375 cells as well as in the triple-negative breast cancer cells MDA-MB-231, alantolactone exerts its antiproliferative and apoptosis-inducing effect by the inhibition of signal transducer and activator of transcription 3 (STAT3) signaling pathway." (PMID 39407585, 2024). "Identifying them and assessing their relevance in different cancer subtypes where the two pathways are known to play a key pathogenic role could in turn support the pre-clinical experimentation of combinations of STAT3 and JNK1 inhibitors in triple-negative breast cancer." (PMID 30654518, 2019). "Thus, Stat3 is a potential high-yield target for drug development to treat several cancers including triple-negative breast cancers for which there are currently no currently approved molecularly targeted therapies." (PMID 22879872, 2012).
Sepsis (191 papers, 2009 to 2026). Sepsis is defined as life-threatening organ dysfunction caused by a dysregulated host response to infection. "In acute lung injury caused by sepsis, phosphorylated STAT3 recruits EP300 to form a complex that promotes the acetylation of histones H3 and H4 at the NLRP3 promoter, leading to cellular pyroptosis." (PMID 41513612, 2026). "In conclusion, this study identified candidate sepsis genes, Rela and Stat3, and developed a diagnostic model incorporating essential genes for comprehensive classification." (PMID 40181843, 2025). "MCM3AP-AS1 functioned as a competing endogenous RNA, effectively regulating miR-501-3p/STAT3/NF-κB pathway, thereby ameliorating inflammation and mitochondrial function, then alleviating sepsis- caused cardiomyopathy." (PMID 40181954, 2025). "miR-223 negatively regulated the expression of STAT-3 and IL-6 in mouse hearts. loss of miR-223/-223* causes an aggravation of sepsis-induced inflammation, myocardial dysfunction and mortality." (PMID 40041174, 2025). "Colivelin, a STAT3 agonist, has been reported to have therapeutic potential for the treatment of sepsis-associated endothelial dysfunction." (PMID 39903516, 2025). "Curcumin inhibits the activation of the JAK2/STAT3 signaling pathway, suppressing the expression of downstream inflammatory mediators and mitigating tissue damage associated with sepsis." (PMID 41041277, 2025). "Previous studies have demonstrated the diagnostic value of STAT3 in sepsis-induced myocardial disease and sepsis-related respiratory distress syndrome." (PMID 37564869, 2023). "Meanwhile, the representative endotoxin, LPS, triggers excessive production of the STAT protein family, specifically STAT3, which is associated with the upregulation of LPS-binding protein, causing an amplification of inflammation in sepsis." (PMID 35795403, 2022). "Taken together, our data demonstrate that Serinc2 functions as an endogenous protector against sepsis-associated ALI through suppression of STAT3, p38, and ERK pathways and activation of the Akt pathway." (PMID 35799194, 2022). "ZJF reversed the lung injury caused by sepsis through inhibiting JAK1/STAT3 expression and subsequently reducing inflammatory mediator production." (PMID 33506010, 2021). "It was previously reported that STAT3 signaling was involved in skeletal muscle wasting in cancer cachexia and sepsis, and recent studies showed that STAT3 activation causes C/EBPδ to promote muscle wasting." (PMID 34003837, 2021). "Previous studies have indicated that IL-6, the most well-known traditional activator of STAT3, was a hallmark of many human chronic inflammatory states, including sepsis, rheumatoid arthritis (RA), and inflammatory bowel disease (IBD)." (PMID 32733162, 2020). "Macrophage/neutrophil-specific STAT3 deletion mice were more susceptible to endotoxemia and sepsis associated with higher systemic inflammation, weaker bacterial clearance, more severe multiple organ dysfunction and increased mortality." (PMID 32641132, 2020). "The activation of STAT3 is crucial for the activation of proteolytic pathways in muscle atrophy caused by different types of cancer and sterile sepsis." (PMID 31293430, 2019). "In this sepsis model, macrophage metabolic reprogramming is dependent on the STAT3/HIF1α/glycolysis axis and inhibition of glycolysis ameliorates susceptibility to sepsis." (PMID 30249998, 2018). "In this regard, the Signal transducer and activator of transcription 3 (STAT3) signalling axis in hepatocytes has been identified as a profound negative regulator of the sepsis-associated, dysregulated inflammatory response." (PMID 28533521, 2017). "Surprisingly, induction of IL-6, the main cytokine responsible for hepatic STAT3 activation during sepsis, was reduced in TR deficient mice." (PMID 27484112, 2016).
Sepsis (continued). "To study if plasminogen deficiency affect STAT3 activation, we measured the levels of phosphorylated and total STAT3 in spleen neutrophils obtained 24 h after infection and sepsis induction." (PMID 21931850, 2011). "Through bioinformatics analysis, we identified five genes associated with ferroptosis—MAPK3, MAPK8, PPARG, PTEN, and STAT3—that may contribute to sepsis-related tissue damage." (PMID 40070882, 2025). "Previous data suggested that STAT3 may be a key regulatory gene in the potential dysfunction induced by sepsis-associated acute respiratory distress syndrome." (PMID 40177399, 2025). "GLP-1 RAs may reduce sepsis risk by suppressing inflammation, including cytokine production and monocyte adhesion, as shown in animal studies via STAT3 and NLRP3 pathways." (PMID 40863575, 2025). "In addition, exosomes from bone marrow-derived mesenchymal stem cells, serving as carriers for delivering miR-125b-5p, can downregulate STAT3, thereby inhibiting macrophage pyroptosis and alleviating sepsis-associated ALI." (PMID 40028334, 2025). "Furthermore, recent research has highlighted the potential importance of the STAT3 axis in facilitating NET release in a sepsis model and its contribution to sepsis-associated encephalopathy." (PMID 38671938, 2024). "In rat (Rattus norvegicus), the YTHDF1 knock-down macrophages could protect the brain injury and reduce the inflammation caused by severe sepsis via inhibition of JAK2/STAT3 expression." (PMID 37298300, 2023). "Notably, p-STAT3 has been implicated in systemic inflammation, acute lung injury, and vascular leakage in sepsis." (PMID 37978525, 2023). "Previous studies proposed that STAT3 pathway activation was associated with the development of muscle atrophy in various endogenous diseases including sepsis, cancer, chronic obstructive pulmonary disease, myocardial failure, chronic kidney diseases, and degenerative muscle disease." (PMID 36588738, 2022). "In the spleen, mesenchymal stem cells downregulate the expression of α7nAChRs and reduce the ratio of phosphorylated STAT3 to total STAT3, thereby reducing the intensity of systemic inflammation and preventing organ damage caused by sepsis, as well as in the heart." (PMID 34776789, 2021). "LysMcre/Stat3flox/- mice which were designed for cell-specific STAT3 disruption in macrophages and neutrophils had overwhelming inflammatory responses to bacterial endotoxin, which made them very susceptible to endotoxemia and sepsis." (PMID 33754049, 2021). "As previous work has demonstrated that STAT3 plays a presumptive role in inhibiting GNG 22, we next investigated whether lower blood glucose was associated with higher hepatic STAT3 activity in sepsis rats." (PMID 29285858, 2018). "Further correlation analysis revealed that MASP-1 expression was significantly positively associated with IL6/JAK/STAT3 signaling and significantly negatively correlated with checkpoint, ferroptosis, HLA, T-cell co-inhibition, T-cell co-stimulation, and necrosis in trauma and sepsis." (PMID 38384415, 2024). "Notably, these DEPs including Fads2, Fgb, Cypla2, Cyp2e1, Cfb, Serping1, Fgg, Etnppl, Agt, Hsd3b5, Gnmt, A2m, Pck1, Stat3, Ptpn1, Scd1, Slc2a1, and Uox were key genes in liver sepsis, which maybe associated with inflammation in sepsis." (PMID 37255592, 2023). "In summary, PRMT5 regulates sepsis-induced lung injury through a methylation-dependent JAK1/STAT3 pathway, serving as a potential target for clinical intervention." (PMID 41568710, 2026). "In sepsis-induced acute lung injury, phosphorylated STAT3 recruits EP300, promoting acetylation of the histone region of the NLRP3 gene and thereby facilitating pyroptosis." (PMID 41513612, 2026). "Mechanistically, IFI27 suppresses Treg function and enhances ferroptosis in lung epithelial cells through inhibition of the IL-10/STAT3 signaling pathway, thereby aggravating sepsis-induced lung injury." (PMID 42099627, 2026).